TBX3 (T-box transcription factor 3)
Diseases named in the same sentence as TBX3 in open-access papers (continued):
Sharing a sentence is not in itself a finding about the gene and the disease.
melanoma (continued). "The antifungal piroctone olamine, previously identified as a TBX2‐/3‐targeting drug in melanoma and rhabdomyosarcoma, inhibited the levels of TBX2 and TBX3 and recapitulated the phenotypes observed when they were knocked down in 2D and 3D PDAC cell culture models." (PMID 40717225, 2025). "Interestingly, niclosamide, piroctone olamine and pyrvinium pamoate inhibit the Wnt/β-catenin pathway and were recently shown to inhibit TBX2 and TBX3 levels and to exert anti-cancer activity in TBX2/3-driven melanoma and rhabdomyosarcoma." (PMID 39912718, 2025). "Indeed, the abundant expression of USP15 and TBX3 concurs apparently through BRAFV600E positive cancer cells, such as melanoma cells A2058, OCM-1, A375, besides thyroid cancer cells K1, BCPAP, 8505 C." (PMID 38750011, 2024). "Besides, TBX3 was up-regulated by BRAFV600E-induced MAPK pathway activation and promotes melanoma migration via repressing E-cadherin, which correlates TBX3 with BRAFV600E associated tumorigenesis." (PMID 35332119, 2022). "Mir-137 can inhibit the migration and invasion of melanoma cells 45–47 by targeting various mRNAs such as PIK3R3, TBX3, c-Met, YB1, EZH2, and MITF, and inhibit the proliferation and promote the apoptosis of melanoma cells by competitive binding to genes such as SLC1A5, GLO1, CDK6, etc.." (PMID 33194692, 2020). "Importantly, when AKT3 was silenced by siRNA (siAKT3) in ME1402 and MM200 VGP melanoma cells total AKT protein was undetectable and this corresponded with a decrease in TBX3 protein levels." (PMID 25595898, 2015). "We therefore tested this by investigating whether there was an inverse correlation between TBX3 and E-cadherin protein levels in ME1402 VGP melanoma cells in which the AKT pathway was inhibited." (PMID 25595898, 2015). "To explore whether AKT3 was therefore responsible for upregulating TBX3 levels, we firstly performed qRT-PCR to confirm that it was the predominant AKT isoform in our melanoma cell lines." (PMID 25595898, 2015). "E-cadherin is a known TBX3 target and its expression has been shown to be inhibited by the AKT pathway in melanoma cells suggesting that AKT-induced phosphorylation of TBX3 may be required to inhibit E-cadherin levels in these cells." (PMID 25595898, 2015). "Tbx3 was found to repress E-cadherin in melanoma cells, but it does not appear to do so in mammary epithelial cells." (PMID 25343378, 2014). "Using in vitro and in vivo assays we demonstrate here for the first time that overexpressing TBX3 in non-tumourigenic early stage melanoma cells is sufficient to promote tumour formation and invasion." (PMID 24098938, 2013). "This study demonstrates for the first time that increased levels of TBX3 are sufficient to promote tumour formation and invasion of non-tumourigenic melanoma cells in vivo." (PMID 24098938, 2013). "Indeed, TBX3 has been shown to be regulated by AKT3 and AKT1 (key mediators of PI3K signalling) through posttranslational phosphorylation resulting in stabilisation and nuclear localisation in melanoma and fibrosarcoma cells respectively." (PMID 39403898, 2024). "Interestingly, while highly homologous, in cancers where they are both overexpressed, such as melanoma, TBX2 and TBX3 have central but distinct roles where TBX2 functions as a potent growth promoting factor and TBX3 contributes to tumour formation and invasion." (PMID 39403898, 2024). "Indeed, in melanoma, AKT3 is the most abundant isoform and AKT phosphorylation of TBX3 enhances protein stability, nuclear localisation and transcriptional activity; in fibrosarcoma and chondrosarcoma, AKT1 is the predominant isoform and it maintains high levels of TBX3." (PMID 32098189, 2020). "MG132 treatment of TBX3 negative melanoma cells could not however rescue TBX3 levels suggesting that TBX3 was repressed in these cells by a mechanism not involving protein degradation by the proteasome 26S." (PMID 25595898, 2015).
melanoma (continued). "Also, Peres and prince have demonstrated that increased levels of TBX3 are sufficient to promote tumor formation and invasion of non-tumorigenic melanoma cells in vivo." (PMID 25287937, 2014). "Furthermore, we have shown that knocking down TBX3 in vertical growth phase (VGP) and metastatic melanoma cells inhibits cell migration and tumour formation and TBX3 was demonstrated to repress the E-cadherin gene which is characteristically downregulated in VGP melanoma." (PMID 24098938, 2013). "Due to a lack of reliable and high‐grade antibodies against TBX2 and TBX3 for immunofluorescence, this study used a tetracycline‐on (Tet‐On) system that enabled the inducible expression of 3XFLAG‐tagged TBX2 or 3XFLAG‐tagged TBX3 in the 501mel human melanoma cell line." (PMID 39403898, 2024). "However, it will be important to determine whether these are the only mechanisms responsible for the role of TBX3 in melanomas and whether AKT3 can lead to an increase in TBX3 levels regardless of BRAF status." (PMID 25595898, 2015).
ulnar-mammary syndrome (40 papers, 2007 to 2026). "Several human T-box genes show haploinsufficiency in the limb, including Tbx5 and Tbx3 that, when mutated, cause Holt-Oram and ulnar-mammary syndrome, respectively." (PMID 41981936, 2026). "In humans, inborn errors of cholesterol synthesis induce different malformation syndromes, many of which present clinically with underdeveloped limbs, mirroring features of ulnar mammary syndrome caused by germline TBX3 mutations." (PMID 40638249, 2025). "Ulnar mammary syndrome (UMS) results from heterozygous variants in the TBX3 gene and impacts limb, tooth, hair, apocrine gland, and genitalia development." (PMID 39320041, 2024). "In humans, loss of function mutations in TBX3 result in the Ulnar-Mammary Syndrome (UMS), an autosomal dominant condition characterized by mammary gland hypoplasia and other congenital anomalies." (PMID 38081972, 2023). "TBX3 was first reported to be implicated in ulnar-mammary syndrome, a rare pleiotropic disorder with defects of the upper limb, tooth, and genitalia, and hypoplasia of the mammary and apocrine glands." (PMID 36923312, 2022). "Accordingly, mutation or deregulation of TBX3 underlies developmental diseases, like the Ulnar-mammary syndrome." (PMID 34807923, 2021). "As a member of the T-box gene family, TBX3 plays an important role in embryonic development and some mutations in this gene cause ulnar-mammary syndrome." (PMID 31940795, 2020). "Germline mutations or haploinsufficiency of TBX3 results in ulnar-mammary syndrome (UMS, OMIM 181450), characterized by mammary gland hypoplasia, apocrine gland, dental, and genital defects, emphasizing its broad expression profile." (PMID 31570773, 2020). "In humans, mutated TBX3 is associated with the ulnar-mammary syndrome, which can include genital abnormalities including micropenis, delayed puberty and cryptorchidism." (PMID 31719618, 2019). "For example, TBX3, a gene responsible for the ulnar mammary syndrome, lies directly close to its associated ngDMR." (PMID 31878147, 2019). "TBX3, a member of the T-box gene family, causes Ulnar-mammary syndrome which is a rare disorder characterized by distinct chin and nose shape together with many other abnormal morphological changes." (PMID 31763980, 2019). "Mutations in the T-box transcription factor, TBX3, have previously been identified as the genetic cause of ulnar-mammary syndrome (UMS), characterized by distinctive defects in posterior forelimb bones." (PMID 27491074, 2016). "Heterozygous mutation of TBX3 causes Ulnar-mammary syndrome (UMS), initially described as a constellation of congenital limb defects, apocrine and mammary gland hypoplasia, and genital abnormalities." (PMID 27046536, 2016). "Tbx3 mutations are found in Ulnar mammary syndrome in human patients, which is characterized by mammary gland hypoplasia." (PMID 26215676, 2015). "In humans, hypomorphic germline mutations in the Tbx3 gene are the cause of Ulnar-Mammary Syndrome in which reduced activity of Tbx3 results in reduced breast development, in addition to other developmental defects." (PMID 25343378, 2014). "Germ-line mutations in the Tbx3 gene give rise to Ulnar-Mammary Syndrome (comprising reduced breast development) and Tbx3 is required for mammary epithelial cell identity in the embryo." (PMID 25343378, 2014). "Heterozygous mutations in TBX3 result in ulnar-mammary syndrome (UMS) in humans, which results in severe mammary gland hypoplasia, accentuating its importance during this developmental stage." (PMID 25350852, 2014). "The transcription factor TBX3 plays critical roles in development and TBX3 mutations in humans cause Ulnar-mammary syndrome." (PMID 23844108, 2013). "Tbx3 is a TF and mutations in Tbx3 have been identified as responsible for the development of ulnar-mammary syndrome in humans." (PMID 23714178, 2013). "In humans, heterozygous mutations in TBX3 result in Ulnar-Mammary Syndrome, which is characterized by mammary hypoplasia." (PMID 24260306, 2013).
ulnar-mammary syndrome (continued). "In humans, TBX3 mutations cause ulnar-mammary syndrome (UMS) which is characterized by mammary gland hypoplasia, abnormal limb development and various abnormalities of the heart and genitalia." (PMID 23082988, 2012). "In humans, haploinsufficiency of TBX3 causes the Ulnar Mammary syndrome (UMS), a pleiotropic disorder that typically presents defects in limb, mammary gland, tooth, hair and apocrine gland development." (PMID 17460765, 2007). "In ulnar mammary syndrome, they proposed that the pathology responsible for the disruption in testicular descent is linked to dysfunctions in the Wnt/β-catenin signaling pathways attributable to a TBX3 gene mutation." (PMID 40622564, 2025). "Mutations in the TBX3 gene can cause Ulnar-Mammary Syndrome and Holt-Oram Syndrome." (PMID 35846885, 2022). "Furthermore, the majority of ulnar mammary syndrome-associated TBX3 C-terminal mutants that exhibit loss of function have been reported to lack the dominant repression domain." (PMID 27110270, 2016). "TBX3 mutations in humans cause a complex of birth defects called Ulnar-mammary syndrome (UMS)." (PMID 24675841, 2014). "TBX3 mutations in humans cause complex congenital malformations and Ulnar-mammary syndrome." (PMID 24675841, 2014). "The transcription factor TBX3 is critical for human development: heterozygotes bearing point, deletion and insertion mutations in TBX3 have ulnar-mammary syndrome (UMS) consisting of congenital limb defects, apocrine and mammary gland hypoplasia, and dental and genital abnormalities." (PMID 23844108, 2013). "There is one report that over-expression of either Tbx3 or Tbx2 in chick leg buds leads to toes becoming more posterior in character while in human patients with mammary ulnar syndrome, associated with haplo-insufficiency of Tbx3, posterior digits can be lost or abnormally spaced." (PMID 21526123, 2011). "Haploinsufficient TBX3 mutations in humans cause ulnar-mammary syndrome (UMS), which causes a pleiotropic phenotype, including severe reductions of the posterior skeletal elements of the upper extremities." (PMID 38828908, 2024). "In addition, TBX3 (T-box transcription factor 3), an important regulator of muscle and its accessory tissues, exerted an instrumental role in muscle and bone development, and mutations in humans led to Ulnar-mammary syndrome." (PMID 37239410, 2023). "TBX3 haploinsufficiency in human causes ulnar-mammary syndrome (UMS), a genetic disorder characterized by abnormal forelimb and apocrine gland development." (PMID 31596842, 2019). "UMS also referred to as Schinzel syndrome or Pallister ulnar-mammary syndrome can result from either point mutations or deletions of the TBX3 gene." (PMID 27722056, 2016). "Interestingly, Pflugfelder and Fischer also recently reported that two ulnar mammary syndrome associated TBX3 DNA binding domain mutations (H187Y and R130S/G129A) could both abrogate its ability to repress a p21 promoter driving a luciferase reporter." (PMID 27110270, 2016). "TBX3 has been mentioned in relation to ulnar mammary syndrome, pancreatic-related diseases, and cardiac pathologies." (PMID 40622564, 2025). "The clinical characteristics of Ulnar-mammary syndrome (UMS) caused by mutations in TBX3 (T-Box transcription factor 3) were studied and the correlation between genotype and clinical phenotype were analyzed to improve awareness and early diagnosis of the disease." (PMID 36937985, 2023). "In a large German family, TBX3 and TBX5 duplication was reported to be associated with Ulnar-Mammary syndrome." (PMID 35565484, 2022). "T-box transcription factor 3 (TBX3), first characterized in ulnar-mammary syndrome, belongs to T-box transcription factor family and plays critical roles in embryonic development and tumorigenesis." (PMID 35332119, 2022). "Mutations in the human TBX3 and TBX5 genes cause ulnar-mammary syndrome (UMS, OMIM 181450) and Holt-Oram syndrome (HOS, OMIM 142900), respectively." (PMID 30630509, 2019).
ulnar-mammary syndrome (continued). "Our observations with these alleles in mice, and the different types of TBX3 mutations observed in human ulnar-mammary syndrome, suggest that not all mutations observed in humans generate functionally null alleles." (PMID 23844108, 2013). "We further searched the Pubmed database using the terms “(Ulnar-mammary syndrome) or (UMS) or (Schinzel syndrome) or (Ulnar-mammary syndrome of Pallister) and (TBX3)”, from 1976 to 2022, and 82 relevant articles in English were retrieved." (PMID 36937985, 2023). "The patient carrying a contiguous microdeletion of TBX5 and TBX3 genes displays features of Holt–Oram Syndrome (HOS) and ulnar-mammary syndrome (UMS)." (PMID 27722056, 2016). "Expression of Tbx1 and Tbx3, the DiGeorge/velo-cardio-facial (DGS) and Ulnar-mammary syndrome (UMS) disease genes, was expanded in miR-17-92 mutant craniofacial structures." (PMID 24068957, 2013).
bladder cancer (9 papers, 2011 to 2025). "For instance, methylation of TBX2 and TBX3 were shown to be associated with prognosis and predict progression in bladder cancer." (PMID 30866410, 2019). "Knockdown of Tbx3 in rat bladder carcinoma cell lines resulted in a lower growth rate and more apoptotic cells than controls, suggesting that Tbx3 promotes cell proliferation and is a negative regulator of apoptosis." (PMID 22039763, 2011). "This strategy identified a large module of Luminal TFs, including known Luminal-associated TFs (e.g., FOXA1/GATA3/PPARG), as well as TFs with yet unexplored roles in Luminal bladder cancer biology (e.g., HES1, FOXQ1, ZBTB7C, MECOM, GRHL2/3, and TBX3)." (PMID 36944729, 2023). "For example, TBX1 plays a tumor-promoting role in basal cell carcinoma and TBX3 plays a tumor-promoting role in basal cell carcinoma in HCC, melanocytoma, and bladder cancer, whereas TBX1 and TBX3 exert a tumor-suppressing effect on thyroid cancer and fibrosarcoma, respectively." (PMID 38965548, 2024). "In adult tissues, TBX3 is mainly expressed in cancers of epithelial or mesenchymal origin, such as head and neck SCC, GC, ovarian cancer, cervical cancer (CC), pancreatic cancer, bladder cancer, and HCC." (PMID 38965548, 2024).
breast tumors (9 papers, 2012 to 2025). "The identification of TBX3 mutations in breast tumors samples suggests that TBX3 is a driver gene in BC." (PMID 35637532, 2022). "Stephens and colleagues, by exome sequencing of breast tumor samples, identified five different mutations in TBX3, all affecting the DNA-binding T-domain." (PMID 26579496, 2015). "Further studies will be necessary to characterize the role and biological significance of TBX3 mutations in breast tumors and how they synergize with estrogen to drive cancer." (PMID 25350852, 2014). "Furthermore, somatic TBX3 mutations in primary breast tumors are predominantly loss-of-function through impaired transcriptional repression." (PMID 31910858, 2020). "The role of TBX3 has been investigated in liverand breast tumors, but to our knowledge,only one study has examined the function of this factor inprostate cancer cells." (PMID 41164275, 2025). "A stronger correlation was observed between GATA3 and TBX3 expression in normal breasts as compared with the breast tumor samples." (PMID 31910858, 2020). "Furthermore, TBX3 overexpression has been observed in primary breast tumors and BC cell lines with elevated expression in estrogen receptor-positive tumor cells." (PMID 35637532, 2022). "Breast tumors with higher TBX3 expression levels have greater recurrence rates." (PMID 33217982, 2020).